MIR1972-2 (microRNA 1972-2)
Synonyms: hsa-mir-1972-2
Gene: MicroRNA gene on chromosome 16 (70,030,346 to 70,030,422, forward strand). Ensembl gene ENSG00000239118.
Homologues: Paralogues in human: MIR1972-1 (100% identical).